CRP (C-reactive protein)
Diseases named in the same sentence as CRP in open-access papers (continued):
Sharing a sentence is not in itself a finding about the gene and the disease.
Insulin resistance (continued). "Following an MD, individuals with low-plasma OEA/PEA at baseline decreased homeostatic model assessment of insulin resistance index (p = 0.01), while individuals with high-plasma OEA/PEA decreased serum high-sensitive C-reactive protein (p = 0.02)." (PMID 33763720, 2021). "A large number of studies have shown the positive correlation between CRP, WBC, insulin resistance, BMI, and visceral fat." (PMID 32219132, 2020). "In the MHW group, insulin, homeostatic model assessment of insulin resistance (HOMA-IR), γ-glutamyltransferase (GGT), high-sensitivity C-reactive protein (hs-CRP), and interferon (IFN)-γ showed significant increases compared to those in the other groups." (PMID 32346379, 2020). "We also evaluated the lipid profile, insulin and glucose levels, homeostatic model assessment of insulin resistance (HOMA-IR), and C-reactive protein (CRP) levels." (PMID 31973121, 2020). "α‐hydroxy VLCFA‐GM3 was also strongly correlated with indicators of insulin resistance and chronic inflammation (ALT, HOMA‐IR, CRP) (and EV1G–J)." (PMID 32378734, 2020). "Primary endpoints were the effects on body mass index standard deviation score (BMI-SDS) and homeostatic model assessment of insulin resistance (HOMA-IR), key secondary endpoints were the levels of C-reactive protein (CRP), leptin, and adiponectin." (PMID 32154197, 2020). "However, the intensity of inflammation, as measured with CRP, was not directly associated with elevated CV risks in our patients, nor was insulin resistance, which is another pathophysiological mechanism closely related to both endothelial and liver dysfunction." (PMID 33218157, 2020). "Exploratory outcomes were insulin resistance as assessed by homeostatic model assessment of insulin resistance (HOMA-IR) and inflammation as assessed by C-reactive protein (CRP), as well as serum uric acid and serum transaminases." (PMID 32033078, 2020). "Multivariable adjustment included insulin resistance (IR), smoking, anti-psychotic treatment (DDD), age, sex, BMI, hs-CRP (CRP), and MPO." (PMID 32754070, 2020). "PTX3 was positively correlated with hs-CRP, body mass index (BMI), fasting plasma glucose (FPG), and homeostasis model assessment of insulin resistance (HOMAIR)." (PMID 31721795, 2019). "Glycosylated hemoglobin A1c (HbA1c), fasting plasma glucose (FPG), 2-hour plasma glucose (2hPG), lipid profiles, homeostatic model assessment insulin resistance (HOMA-IR), and hs-CRP were measured." (PMID 31956660, 2019). "The HbA1c levels, serum ferritin, hemoglobin (Hb), insulin, Homeostatic Model Assessment of Insulin Resistance (HOMA-IR), C-Reactive Protein (CRP), lipid profiles, and uric acid levels were compared between the groups." (PMID 31372137, 2019). "Obese pre-DM patients showed high values of glucose, insulin resistance (HOMA-IR), C reactive protein (CRP), nitrotyrosine, tumor necrosis factor-α (TNF-α) and interleukin 6 (IL-6), and low values of insulin (p < 0.05)." (PMID 30845774, 2019). "Body mass index, visceral obesity, insulin resistance, and HDL and LDL cholesterol have been reported to be important correlates of CRP and other inflammatory markers." (PMID 31287027, 2019). "Omega-3 fatty acids were found to reduce fasting plasma glucose (FPG), homeostatic model of assessment for insulin resistance (HOMA-IR), and high-sensitivity C-reactive protein (hs-CRP) in the women with gestational diabetes." (PMID 31956660, 2019). "Across worsening CKD stages, we noted increased concentrations of triacylglycerols (TAG), glucose, insulin, homeostatic model of insulin resistance (HOMA IR), C-reactive protein (CRP) and K+." (PMID 31109090, 2019). "In recent studies, chemerin was also found to positively correlate with systemic inflammation biomakers (i.e. CRP, WBC count), insulin resistance, dyslipidemia and hepatic disorders in incident and maintenance HD patients." (PMID 31337804, 2019).
Insulin resistance (continued). "Triglycerides, insulin, homeostasis model assessment-insulin resistant (HOMA-IR), leptin, C-reactive protein (CRP), and EDF marker intercellular adhesion molecule 1 (ICAM-1) were significantly higher in obese children and adolescents." (PMID 30572569, 2018). "In this sense, prior studies suggest a positive relationship between markers of chronic inflammation, including CRP, IL-1β, IL-6, and TNF-α, and insulin resistance." (PMID 29561774, 2018). "Like CRP, TNF-α is considered a link between hypertriglyceridemia, inflammation, and insulin resistance." (PMID 29189992, 2018). "Homeostasis model assessment for insulin resistance (HOMA-IR) was used as an IS parameter and C-reactive protein (CRP) was measured to represent the inflammatory status." (PMID 30294302, 2018). "Systemic inflammation, which increases levels of CRP, stimulates pathological arterial intimal changes which are part of the basis for later CVD, while insulin resistance forms the key pathological change leading to T2DM." (PMID 29273941, 2018). "Elevated levels of interleukin 6 (IL-6), C-reactive protein (CRP) and fibrinogen in PD increase insulin resistance." (PMID 30477167, 2018). "Although not statistically significant, there were also clinically meaningful outcomes which included improvements in insulin, homeostatic model assessment of insulin resistance (HOMA-IR), and C-Reactive Protein (CRP)." (PMID 29510546, 2018). "The “inflammatory” type often encompasses an ApoE4 allele carrier, which presents with markers of systemic and cerebral inflammation such as C-reactive protein (CRP) and IL-6 levels, insulin resistance and hyperhomocysteinemia." (PMID 29249963, 2017). "Blood samples were collected over the 14-week study and analyzed for glucose, lipid profile, and CRP, lipid particles, TNF-α, IL-10, insulin, and insulin resistance (IR)." (PMID 29410955, 2017). "We evaluated other lipid profiles related to insulin resistance and micro-inflammation such as apoB, small dense LDL, RLP-C, and high-sensitivity CRP (hsCRP)." (PMID 28646901, 2017). "For this, human CRP transgenic mice were fed standard chow, a lard-based HFD, HFD+rosuvastatin or HFD+rosiglitazone for 42 weeks to study effects on insulin resistance; plasma inflammatory markers and adipokines; and renal pathology." (PMID 28588299, 2017). "To study the influence of inflammation on hepatic insulin resistance, we determined the levels of MCP-1, C-reactive protein (CRP), IL-6 and TNF-α." (PMID 29028831, 2017). "In 2008-2010, leptin, the homeostasis model assessment of insulin resistance (HOMA-IR) and C-reactive protein (CRP) were measured." (PMID 28400989, 2017). "The GDM animal model showed signs of insulin resistance where expressions of both proinflammatory cytokines (IL-6 and TNF-α), PCK-1, and serum CRP level were higher than control." (PMID 27379252, 2016). "Systemic inflammation, with elevated markers such as C-reactive protein (CRP), tumor necrosis factor-α (TNF-α) and interleukin-6 (IL-6), plays an important role in both, the progression of COPD and the development of insulin resistance." (PMID 27335596, 2016). "The intake of L. paracasei F19 did not modulate any metabolic markers (homeostasis model assessment of insulin resistance (HOMA-IR), Matsuda index, CRP, and lipid profile) compared with the placebo." (PMID 27304953, 2016). "Based on model 2, model 3 further introduced other related factors including age, BMI, W, SBP, DBP, HbA1c, homeostasis model assessment for insulin resistance (HOMA-IR), TG, HDL-c, LDL-c, and CRP into analyses." (PMID 27270834, 2016). "GDM rats showed possible insulin resistance as evidenced by high expression of proinflammatory cytokines, PCK-1 and CRP." (PMID 27379252, 2016). "All were evaluated for anthropometric parameters, blood pressure, metabolic variables, homeostatic model assessment of insulin resistance (HOMA-IR), adiponectin, leptin, C-reactive protein, and genotyping." (PMID 26561012, 2015).
Insulin resistance (continued). "In the correlation analysis, BMI percentile was positively correlated with insulin resistance (fasting insulin level and HOMA-IR) and inflammatory markers (hs-CRP, MCP-1, TNF-α, PAI-1, and leptin levels) but negatively correlated with the adiponectin level." (PMID 26011530, 2015). "In present study,there was a positive correlation between hsCRP and ALT as well as ferritin only in alpha thalassemia group but we didn’t find any relationship between insulin resistance and ALT, CRP and ferritin." (PMID 25722965, 2015). "The hazard ratio model was adjusted for insulin resistance, triglyceride, HDL-cholesterol, total cholesterol, log hs-CRP, and creatinine." (PMID 26543300, 2015). "We analyzed the correlations of glucose tolerance and insulin resistance with the fasting levels of 10- and 12-(Z,E)-HODE/LA, RBP4, glycoalbumin, adiponectin, leptin, and hs-CRP." (PMID 26132231, 2015). "Fasting insulin levels, value of homeostasis model assessment of insulin resistance (HOMA-IR), and serum high sensitive C-reactive protein (hs-CRP) levels were evaluated." (PMID 26599361, 2015). "First, BMI percentile was positively correlated with insulin resistance (fasting insulin and HOMA-IR), lipid profiles (LDL-c, TG and TC), and inflammatory markers (hs-CRP, MCP-1, TNF-α, PAI-1, and leptin) but negatively correlated with adiponectin level." (PMID 26011530, 2015). "Levels of C-reactive protein (CRP), a sensitive marker of systemic inflammation, were found to be elevated in individuals with features of metabolic syndrome and insulin resistance." (PMID 25105149, 2014). "The major finding of the present study was that neither CET nor SIT has any significant effect on serum levels of I-6, IL-10, CRP, WBC, and insulin resistance index." (PMID 23725447, 2013). "The major findings of this study are that the addition of pioglitazone to stable DMARD treatment for RA improves insulin resistance, as measured by HOMA, and modestly reduces RA disease activity, as measured by DAS28-CRP, patient-reported GH and CRP levels." (PMID 24020899, 2013). "The increased risk for cardio-metabolic diseases in NAFLD is caused by different factors among which hepatic overproduction of glucose, VLDL, inflammatory factors, C-reactive protein (CRP), and coagulation factors and by the presence of insulin resistance." (PMID 23666091, 2013). "The changes in FBS, insulin,Homeostasis Model Assessment Insulin Resistance (HOMA-IR), hcy, hs-CRP and diastolic blood pressure before and after Ramadan were not significant (P >0.05, t test)." (PMID 22963582, 2012). "Patients with high baseline insulin resistance demonstrated significant improvement in DAS28 (P = 0.013), HAQ (P = 0.012), and CRP (P = 0.007) after 12 weeks of treatment with anti-TNF agents." (PMID 22691241, 2012). "Elevated serum concentrations of C-reactive protein, interleukin IL-6, IL-8, and tumor necrosis factor (TNF)-α are observed in obese individuals with elevated insulin resistance." (PMID 23091306, 2012). "Serum fasting insulin and insulin resistance assessed by HOMA were positively correlated with fibrinogen (r = 0.26; P < 0.05), C-reactive protein (r = 0.29; P < 0.05, and r = 0.35; P < 0.01, resp)." (PMID 21822486, 2012). "The C-reactive protein (CRP), an inflammatory marker, is known to play a role in the insulin resistance." (PMID 22114593, 2011). "IL-6 is responsible for stimulating hepatocytes to secrete C reactive protein and has been proposed to be responsible for the systemic consequences of COPD (insulin resistance, osteoporosis, muscle degradation, and depression)." (PMID 21267454, 2011). "The endpoints of the study were the insulin resistance (IR), the prognostic inflammatory and nutritional index (PINI) and the C-reactive protein (CRP)/albumin ratio." (PMID 21668975, 2011).
Insulin resistance (continued). "Inflammatory factors such as adhesion molecules (ICAM-1 and VCAM-1), CD40 ligands, C-reactive protein (CRP) and myeloperoxidase (MPO) participate in induction of insulin resistance and atherosclerotic disease." (PMID 21247435, 2011). "In conclusion, our findings showed that insulin resistance was associated with CRP levels independent of abdominal obesity in Chinese patients with type 2 diabetes, suggesting that abdominal obesity could only partly explain the link between subclinical inflammation and insulin resistance." (PMID 21167068, 2010). "Consistent with previous reports, BMI, insulin resistance (HOMA) and systemic inflammation (serum CRP levels) were lower in the highest vs. lowest adiponectin quartile (p < 0.001)." (PMID 21143922, 2010). "Our primary outcomes are serum concentrations of leptin, adiponectin, TNF-α, C-reactive protein (CRP), IL-6 and insulin resistance." (PMID 20550712, 2010). "Differences in fasting insulin, insulin resistance, triglyceride, HDL-cholesterol, and C-reactive protein were slightly reduced in size, but all remained strongly statistically significant." (PMID 20421924, 2010). "First, the correlation between CRP and WC was stronger in women than in men (0.25 versus 0.11) in our study; moreover, women have a higher percentage of body fat than men, especially in obese women, so CRP may have a greater role in the development of insulin resistance and type 2 diabetes in women." (PMID 21076541, 2010). "The reduction in inflammation induced by PAZ, as evidenced by strongly decreased levels of C-reactive protein (mean change -6.20 mg/L; -57%), should be considered here, as it may be responsible for improving blood sugar profiles through a reversal of the autoimmune component of insulin resistance." (PMID 17803818, 2007). "The C-reactive protein-triglyceride-glucose index (CTI), as a novel composite marker reflecting both insulin resistance and systemic inflammation, may serve as a useful tool for OA risk assessment and management." (PMID 41995511, 2026). "Mediation analyses identified higher inflammation (CRP), but not insulin resistance (HOMA‐IR), as a significant mediator between CRS and incident MetS." (PMID 40987451, 2026). "The following parameters were measured in peripheral blood samples: glucose, triglycerides, total cholesterol, high-density lipoprotein cholesterol (HDL-c), LDL-c, glycated hemoglobin (HbA1c), insulin, C-reactive protein (CRP), and the homeostatic model assessment of insulin resistance (HOMA-IR)." (PMID 39794663, 2025). "Moreover, a study investigating relationship health in cancer dyads demonstrated that one partner’s perception of relationship quality significantly influences the other’s inflammatory markers (e.g., C-reactive protein [CRP]) and insulin resistance." (PMID 40526697, 2025). "Meta-analyses further confirm that concurrent training reduces insulin resistance—as assessed by the homeostasis model assessment of insulin resistance (HOMA-IR)—and lowers glycated hemoglobin (HbA1c) and C-reactive protein (CRP) in individuals with T2DM and who are overweight/obese." (PMID 41228432, 2025). "Similarly, stratification according to insulin resistance (HOMA-IR < 2.0 vs. ≥2.0) demonstrated significant differences in PCSK9 and CRP concentrations, Castelli indices I and II, and the TyG index." (PMID 41516208, 2025). "Several investigations have indicated a notable decrease in serum lipid profiles, fasting glucose levels, insulin resistance, insulin, HbA1c, interleukin‐6, TNF‐α, CRP, and liver enzymes aspartate aminotransferase, alanine transaminase after consumption of propolis and increase HDL‐C." (PMID 41245948, 2025). "CRP and ESR are also important inflammatory markers in COPD that promote the expression of inflammatory cells during acute exacerbations of COPD symptoms and enhance insulin resistance leading to T2DM." (PMID 40895616, 2025).
Insulin resistance (continued). "Currently, the features are mainly anthropometric and dietary indicators, without fully integrating inflammatory indicators such as C-reactive protein, metabolic markers such as insulin resistance index, and genomic data." (PMID 41438294, 2025). "CRP, an acute-phase protein produced by the liver, promotes the inflammatory response by increasing the synthesis of TNF-α and IL-6, which in turn contributes to insulin resistance." (PMID 40842498, 2025). "In all participants, anthropometric measurements and the following laboratory tests were performed: fasting plasma glucose, glycated hemoglobin (HbA1c) and serum iron, lipid profile, insulin, Homeostatic Model Assessment for Insulin Resistance (HOMA-IR), C-reactive protein (CRP), ERFE and hepcidin." (PMID 41156458, 2025). "Our findings demonstrate that elevated CRP-TyG index (CTI), reflecting the combined burden of systemic inflammation and insulin resistance, exhibits an independent and linear negative association with hepatic synthetic function." (PMID 41458520, 2025). "Therefore, the current investigation was conducted to explore the correlations between depression, anxiety, and CFS due to long COVID and CRP and PGE2, GAL-GALR1 signaling, insulin resistance, PAI1 and IGF1, and neuronal damage markers." (PMID 40048451, 2025). "While FBG is essential for assessing insulin resistance and hs-CRP is useful for measuring systemic inflammation, neither captures the intricate relationship between lipid metabolism and atherosclerotic risk as well as AIP." (PMID 40282902, 2025). "Unlike previous single indexes, which could only reflect inflammation or insulin resistance to a limited extent, our study’s innovative CTI index integrates the CRP and TyG indexes." (PMID 40988273, 2025). "With 1μg/ml CRP-XL alone, the inhibition of PAC-1 by 10 nmol/l PGI2 in those with advanced insulin resistance was significantly reduced compared with those with normal insulin sensitivity (28 ± 9% vs 52 ± 2% p<0.001), which was also evident with higher PGI2 concentration." (PMID 40304758, 2025). "Key metabolic and inflammatory markers such as insulin resistance, C-reactive protein, and interleukin-6 were not measured." (PMID 40688878, 2025). "PTX3 was positively correlated with hs-CRP, body mass index, fasting blood glucose, and HOMA-IR, suggesting that inflammation and oxidative stress may be involved in the development of insulin resistance in GDM." (PMID 41488068, 2025). "“Very-low” quality applied to HC, WC, high-density lipoprotein cholesterol (HDL-C), Homeostatic Model Assessment for Insulin Resistance (HOMA-IR), FSH, LH, DHEAS, free androgen index (FAI), high-sensitivity C-reactive protein (hs-CRP), nitric oxide (NO), and total antioxidant capacity (TAC)." (PMID 39857760, 2025). "Moreover, hsCRP and the TyG index have been used to develop the CRP-TyG index (CTI), synchronously reflecting the inflammation and insulin resistance status given the close correlation between inflammation and insulin resistance." (PMID 38715129, 2024). "We observed that participants with insulin resistance, dyslipidemia, and MetS showed higher plasma CRP concentrations than those without these metabolic conditions." (PMID 39452916, 2024). "Insulin resistance and T2DM are correlated with sustained low-grade inflammation, and probiotics such as Lactobacillus casei have been demonstrated to lower inflammation indicators, including CRP and TNF-α." (PMID 38931292, 2024). "Additionally, there was a positive correlation found between inflammatory markers (hs-CRP, MCP-1, TNF-alpha, and PAI-1 levels), lipid profiles (LDL-c, TG, and TC levels), and insulin resistance (fasting glucose level, fasting insulin level, and HOMA-IR)." (PMID 38463431, 2024). "Unfortunately, we have not found correlations with other insulin-resistance biochemical markers such as leptin, microalbuminuria or C-reactive protein." (PMID 38734755, 2024).